OR4C46 (olfactory receptor family 4 subfamily C member 46)
Description:
Odorant receptor.
Tractability: Antibody: UniProt places it where antibodies can reach, with medium confidence; UniProt predicts a signal peptide or a membrane-spanning region; its Gene Ontology location is reachable by antibodies, with medium confidence.
Gene: Protein-coding gene on chromosome 11 (54,603,069 to 54,603,998, reverse strand). Ensembl gene ENSG00000185926.
Subcellular location: Cell membrane
Pathways (Reactome):
Sensory Perception: Expression and translocation of olfactory receptors
Gene Ontology:
Molecular function: olfactory receptor activity; G protein-coupled receptor activity
Biological process: detection of chemical stimulus involved in sensory perception of smell; G protein-coupled receptor signaling pathway
Cellular component: plasma membrane; membrane
Genetic constraint (gnomAD): Loss-of-function variants: 17 observed, 8.98 expected, observed/expected ratio (o/e) 1.89, 90% interval 1.2 to 1.97. That is too few expected variants to judge how well the gene tolerates losing a copy. Missense variants: 567 observed, 325.95 expected, observed/expected ratio (o/e) 1.74, 90% interval 1.62 to 1.86. Synonymous variants: 206 observed, 122.09 expected, observed/expected ratio (o/e) 1.69, 90% interval 1.5 to 1.89.
Homologues: Orthologues: dog OR4C10 (86% identical), dog OR4C10C (85% identical), mouse Or4c10 (84% identical), rat Or4c10 (83% identical), dog OR4C10F (82% identical), dog OR4C10E (81% identical), rat Or4c105 (79% identical), rat Or4c10b (79% identical), rat Olr655 (79% identical), mouse Or4c10b (79% identical), rat Or4c105b (78% identical), mouse Or4c105 (77% identical), and 1 more. Paralogues in human: OR4C13 (84% identical), OR4C12 (65% identical), OR4C15 (64% identical), OR4C45 (61% identical), OR4A15 (61% identical), OR4A47 (61% identical), OR4C5 (61% identical), OR4A5 (60% identical), OR4C6 (60% identical), OR4C3 (59% identical), OR4C11 (57% identical), OR4B1 (56% identical), and 116 more.